MMP9 (matrix metallopeptidase 9)
Diseases named in the same sentence as MMP9 in open-access papers (continued):
Sharing a sentence is not in itself a finding about the gene and the disease.
dysplasia (5 papers, 2011 to 2025). A usually neoplastic transformation of the cell, associated with altered architectural tissue patterns. "In the Rip-Tag2 model of islet carcinogenesis, neutrophils expressing MMP-9 mainly exist in the angiogenic islets of dysplasia and tumours, and the short-term depletion of neutrophils significantly reduces the frequency of initial angiogenesis in dysplasia." (PMID 39847394, 2025). "In the specific case of MMP-9, we investigated the role of MMP-9 expression using immunohistochemical analysis in the development and progression of reflux esophagitis- Barrett’s esophagus-dysplasia-adenocarcinoma sequence in the esophagus." (PMID 23202950, 2012). "Increased immunohistochemical expression of MMP-9 in Barrett’s metaplasia-dysplasia-adenocarcinoma sequence as compared to normal tissue suggested its association with esophageal tumorigenesis." (PMID 23202950, 2012). "It was demonstrated that neutrophil and macrophage derived MMP-9 enhanced progression from dysplasia to overt malignancy in a mouse model of skin squamous carcinoma, with reduced MMP-9 delaying angiogenesis within dysplastic areas and reducing the incidence of invasive disease." (PMID 22295111, 2012). "Increased expression of MMP-9 in Barrett with dysplasia compared to non-dysplastic metaplasia indicated that this alteration might be early event in carcinogenesis." (PMID 23202950, 2012).
encephalomyelitis (5 papers, 2011 to 2024). Inflammation of the brain and the spinal cord. "It is known that the production of MMP-9 occurs in, inter alia, endothelial cells and that the inhibition of metalloproteinases may reduce brain capillary damage in encephalomyelitis." (PMID 34638953, 2021).
hearing loss (5 papers, 2018 to 2021). "The expression level of brevican was decreased in rats with noise-induced hearing loss, which was probably mediated by the increased expression level of MMP9 in the primary auditory cortex." (PMID 32334536, 2020). "Likewise, increased MMP9 expression and decreased PNNs in the auditory cortex following hearing loss have also been reported." (PMID 34020590, 2021). "Together, our data motivate further evaluation of the roles other MMPs, in particular MMP-2 and MMP-9, play in interacting with MMP-14 to promote VS growth and development of associated hearing loss in larger datasets." (PMID 32848608, 2020). "Additionally, MMP2, MMP9, and other ECM molecules contribute to cochlear tissue remodeling and blood–labyrinth barrier permeability in noise-induced hearing loss." (PMID 34206364, 2021). "Thus, the increase in MMP9 could be one mediator of RAGE activation and neuroinflammation in the auditory cortex in the noise-induced hearing loss model used in this study." (PMID 34020590, 2021).
Hypercholesterolemia (5 papers, 2013 to 2024). An increased concentration of cholesterol in the blood. "Persistent hypercholesterolaemia was responsible for diffused effacement or further cytoskeletal re‐assembly that was associated with podocyte malfunction, as demonstrated by mutations of SD proteins and increased vimentin and mmp9 expression, and resultant proteinuria." (PMID 27704688, 2017). "Previous studies showed that MMP-2 and MMP-9 were involved in coronary artery wall formation in experimental hypercholesterolemia, which coincides with vasa vasorum neovascularization." (PMID 27526687, 2016).
inflammatory breast carcinoma (5 papers, 2013 to 2024). An advanced, invasive breast adenocarcinoma characterized by the presence of distinct changes in the overlying skin. "In inflammatory breast cancer cell lines, depletion of AXL-stabilizing protein TIG1 reduces the expression of Matrix metalloproteinase 9 (MMP9), which has been identified as an essential regulator for the AXL-mediated invasion." (PMID 33954117, 2021). "This analysis performed in the BEVERLY-2 phase II trial identified MMP2 and MMP9 as candidate biomarkers correlated consistently to DFS and OS in patients with HER2-positive inflammatory breast cancer." (PMID 26921265, 2016).
intervertebral disc degeneration (5 papers, 2016 to 2025). "Fifteen days after the induction of intervertebral disc degeneration, significant changes were observed, such as reduction in the expression metalloprotease-9 (MMP9) and interleukins (IL-6 and IL-10)." (PMID 26997908, 2016). "MMP9 high expression may promote intervertebral disc degeneration by driving extracellular matrix degradation and shaping an immune-inflammatory microenvironment, whereas low expression may contribute to the maintenance of energy metabolic homeostasis." (PMID 41346614, 2025).
intrauterine growth restriction (5 papers, 2017 to 2025). "The reduced expression of MMP-2 and MMP-9 in preeclamptic and intrauterine growth restriction (IUGR) placentae has been extensively documented." (PMID 41583211, 2025).
kidney stone (5 papers, 2020 to 2023). "Third, the role of MMP-9 in nephrolithiasis is not completely understood and further experimental studies are nevertheless necessary to explore the specific mechanisms for MMP-9 polymorphism and nephrolithiasis." (PMID 37332754, 2023). "In conclusion, the results of the current study demonstrated a significant association between the variation T allele of the MMP-9-1562C>T polymorphism with the likelihood of developing nephrolithiasis." (PMID 37332754, 2023). "To further assess the functional impact of the MMP-9-1562C>T polymorphism on nephrolithiasis development, we also examined the link between serum MMP-9 levels and risk of nephrolithiasis." (PMID 37332754, 2023). "Association between the MMP-9-C1562T genotypes and multiple stones and recurrence in kidney stone patients." (PMID 37332754, 2023). "The serum MMP-9 was measured in 105 kidney stone patients and 77 controls by enzyme-linked immunosorbent assay." (PMID 37332754, 2023). "Stratification analyses between MMP-9-C1562T genotypes and risk of kidney stone in cases and controls." (PMID 37332754, 2023). "Association between the MMP-9-C1562T genotypes and abnormal biochemical indexes in kidney stone patients." (PMID 37332754, 2023). "We investigated the relationship between the MMP-9-1562C>T SNP (rs3918242) and the risk of nephrolithiasis in a southern Chinese population in this hospital-based case-control study." (PMID 37332754, 2023). "The aim of the research is to evaluate the association between MMP-9-1562C>T polymorphism, MMP-9 serum levels and nephrolithiasis risk." (PMID 37332754, 2023). "Genotype frequencies of MMP-9-C1562T among cases and controls and their associations with kidney stone risk." (PMID 37332754, 2023). "To date, there was one study investigating the association between the MMP-9-1562C>T polymorphism and nephrolithiasis risk in Malaysians." (PMID 37332754, 2023). "To date, there has only been one published report of the association between MMP-9-1562C>T polymorphism and nephrolithiasis risk in Malaysians." (PMID 37332754, 2023). "The homozygote T/T of the C1562T polymorphism of MMP-9 promoter region (rs3918242) was more frequent in nephrolithiasis patients than controls." (PMID 34440695, 2021). "Previous studies of the role of angiogenesis in nephrolithiasis development have focused primarily on the analysis of the MMP-9 polymorphisms." (PMID 34440695, 2021). "Considering the role of MMP-9 in nephrolithiasis, we hypothesized that MMP-9-1562C>T was linked to nephrolithiasis risk in Chinese subjects." (PMID 37332754, 2023). "Association between the MMP-9-C1562T genotypes and biochemical parameters in kidney stone patients." (PMID 37332754, 2023). "Logistic regression analyses on associations between serum MMP-9 levels and risk of kidney stone." (PMID 37332754, 2023). "Thus, we were unable to examine the relationship between CKD, kidney stones and MMP-9-1562C>T polymorphism in more detail." (PMID 37332754, 2023). "The MMP-9-1562C>T polymorphism may be useful as a susceptibility marker for nephrolithiasis as it’s linked to its soluble protein and enhances the possibility of developing nephrolithiasis." (PMID 37332754, 2023). "Our study showed that the MMP-9-1562C>T polymorphism correlates with recurrent nephrolithiasis." (PMID 37332754, 2023). "Additionally, the cleavage products of collagen and osteopontin degradation by MMPs (specifically MMP-9) stimulate a chemotactic response and contribute to inflammatory cell recruitment, which is also associated with kidney stone development." (PMID 34440695, 2021). "The MMP-9-1562C>T polymorphism in association with its soluble protein increased the risk of kidney stone, thus suggesting it could be used as a susceptibility biomarker for nephrolithiasis." (PMID 37332754, 2023). "Patients with nephrolithiasis who carried the CT/TT genotype had serum MMP-9 levels that were notably greater compared to patients with the CC genotype." (PMID 37332754, 2023).
kidney stone (continued). "Nephrolithiasis patients with CT and TT genotypes had significantly higher serum MMP-9 levels than patients with CC genotypes." (PMID 37332754, 2023). "Consistently, in this study, a significant elevation in serum MMP-9 levels was observed in nephrolithiasis patients with the CT/TT genotypes compared with the CC genotype." (PMID 37332754, 2023). "Compared to controls (18.57 ± 5.80 ng/mL), nephrolithiasis patients had significantly higher serum MMP-9 levels (30.17 ± 6.78 ng/mL, p < 0.001)." (PMID 37332754, 2023). "To explore the role of MMP-9 in high calcium concentration-induced kidney stone formation, we first examined the effect of exposure to a high concentration of calcium on the expression of MMP-9 in NRK-52 cells." (PMID 34211634, 2021). "Here, we focused on the role of MMP-9 in kidney stone formation in a high-calcium microenvironment and explored the underlying mechanism and associated regulatory network." (PMID 34211634, 2021). "Our study revealed a novel role for MMP-9 in calcium crystal deposition and kidney stone formation induced by a high calcium concentration." (PMID 34211634, 2021). "We also used a vitamin D-induced hypercalciuria rat model to verify the regulatory role of MMP-9 in high calcium concentration-induced kidney stone formation." (PMID 34211634, 2021). "Moreover, MMP-9 may cause the surface of Randall's plaques to rupture, allowing contact between the hydroxyapatite and pelvic urine, thereby forming the core of calcium salt deposition that leads to kidney stone formation." (PMID 34211634, 2021). "Taken together, the evidence suggests that individuals with the variant T allele may gain MMP-9 function and be more prone to develop CKD, and ultimately increase the susceptibility to nephrolithiasis." (PMID 37332754, 2023). "Moreover, patients with nephrolithiasis who had the CT/TT genotype had significantly higher serum MMP-9 levels than those who had the CC genotype." (PMID 37332754, 2023). "Also, we noted that nephrolithiasis patients had serum MMP-9 levels that were considerably greater than those of controls." (PMID 37332754, 2023). "It should be investigated to see if any further functional polymorphisms in the MMP-9 gene, which have not yet been found, increased the risk of nephrolithiasis." (PMID 37332754, 2023). "Compared to controls, nephrolithiasis patients had significantly higher serum MMP-9 levels." (PMID 37332754, 2023). "Moreover, nephrolithiasis patients with C/T and T/T genotypes were characterised by increased serum MMP-9 levels, TOS, MDA, and uric acid AS compared to nephrolithiasis patients with the C/C genotype." (PMID 34440695, 2021). "This implies that MMP-9 may promote Randall's plaque formation and, consequently, kidney stone formation, by promoting the transfer of crystalline particles to the renal interstitium." (PMID 34211634, 2021). "We have previously shown that exposure to a high calcium concentration can activate the NF-κB signaling pathway by promoting the production and release of intracellular ROS, which, in turn, activated the expression of MMP-9, a target of NF-κB, thereby leading to kidney stone formation." (PMID 34211634, 2021). "Thus, mRNA and protein MMP9 levels were higher in nephrolithiasis patients with the C/C genotype than those with the A/A genotype." (PMID 34440695, 2021). "To further explore whether MMP-9 plays a lithogenic or inhibitory role in kidney stone formation, we knocked down or overexpressed MMP-9 in NRK-52E cells." (PMID 34211634, 2021). "Thus, it’s plausible that MMP-9 play a significant role in the genesis of kidney stone." (PMID 37332754, 2023). "However, the specific mechanism by which MMP-9 promotes kidney stone formation may be complex and warrant further exploration." (PMID 34211634, 2021). "However, the role of MMP-9 in kidney stone formation is unclear." (PMID 34211634, 2021).
kidney stone (continued). "Further studies on the mechanism of MMP-9 and CSE in the formation of nephrolithiasis are warranted in the future." (PMID 37332754, 2023).
knee osteoarthritis (5 papers, 2021 to 2025). "The study showed that a 12-week-long consumption of the fruit extract ameliorated the scores for pain, stiffness and knee function along with decreased blood matrix metalloproteinase-9 (MMP-9) levels in subjects with painful knee osteoarthritis." (PMID 38731572, 2024).
leukocytosis (5 papers, 2014 to 2025). "Since neutrophils are the main source of secreted MMP9 in cancer, we believe that the increased plasma MMP9 in ET is related to the apparent leukocytosis observed in our patients." (PMID 37051288, 2023). "Concomitant changes in MMP-9 or YKL-40 may suggest remodeling or ongoing inflammation, yet most of the markers of acute inflammation (IL-6 and IL-8) resolved, while others persevered (CRP, leukocytosis)." (PMID 36271425, 2022). "In fact, in our study and according to others studies, the infiltration of neutrophils is significantly reduced after G-CSF administration; leukocytosis and MMP-9 release are restricted to the vessel compartment and do not contribute to an exacerbation of brain lesion." (PMID 24885160, 2014).
lipid metabolism disorders (5 papers, 2020 to 2025). "In women, matrix metalloproteinases, specifically MMP-2 and MMP-9, could become markers of lipid metabolism disorders." (PMID 39769504, 2024). "Furthermore, as MMP-9 has been shown to cleave citrate synthase ex vivo, the change and involvement of MMP-9 in lipid metabolism disorders should also be further investigated, along with the role played by the miR-33-5p/ABCA1/CS axis." (PMID 34517822, 2021).
liver cirrhosis (5 papers, 2011 to 2022). "MMP-8 levels and activity (along with MMP-2 and MMP-9) have shown to be elevated in alcoholic patients with stage C liver cirrhosis." (PMID 32414178, 2020). "On the key molecules obtained by analysis and experimental verification, GXZY could reduce the expression of MMP9 in cirrhotic rats and LX2 cells, which affects the process of liver cirrhosis." (PMID 35330838, 2022). "Interestingly, our results differ from previous data of the liver cirrhosis rat model which showed increased MMP-2 and MMP-9 activities following FTS treatment." (PMID 21445359, 2011).
lung squamous cell carcinoma (5 papers, 2014 to 2022).
male infertility (5 papers, 2016 to 2023). The inability of the male to effect fertilization of an ovum after a specified period of unprotected intercourse. "We examined the association between the C-1562T polymorphism in the MMP-9 gene and the risk of male infertility." (PMID 29043698, 2018). "We analyzed the synergism of genotypes and alleles of G-1575A MMP-2 and C-1562T MMP-9 gene polymorphisms on male infertility." (PMID 29043698, 2018). "In addition, a relationship was observed between combined MMP-2 and MMP-9 variant genotypes and male infertility." (PMID 29043698, 2018). "Further studies should be performed with larger sample size together with the determination of MMP-9 and MMP-2 activities to provide more information about the impact of these polymorphisms on male infertility." (PMID 29043698, 2018). "Since MMP-9 levels are influenced by stress and inflammation, the present study was designed to investigate the MMP-9 levels in seminal plasma and its associationwith IL-17 and psychological stress in male infertility." (PMID 33997592, 2021). "Considering the role of MMP-9 in both remodeling and destruction of the extracellular matrix, genetic variations may affect the transcription of the gene and activity of this enzyme, resulting in a propensity towards male infertility." (PMID 29043698, 2018). "Matrix metalloproteinase-9 (MMP-9), interleukin-17 (IL-17) and psychological stress are known to play a role in the pathogenesis of male infertility." (PMID 33997592, 2021). "Most SNP-populated genes related to male infertility include HLA-DQB1 (20 SNPs), HLA-DRB1 (15 SNPs), MTHFR (10 SNPs), BRCA2 (9 SNPs), ACE (8 SNPs), CFTR (6 SNPs), CDH1 (6 SNPs), SRD5A2 (6 SNPs), HLA-DQA1 (5 SNPs) and MMP9 (5 SNPs)." (PMID 29263816, 2016).
myeloid leukemia (5 papers, 2014 to 2023). A clonal proliferation of myeloid cells and their precursors in the bone marrow, peripheral blood, and spleen. "EGCG destabilizes the transcription of MMP-9 to down-regulate its expression in macrophage-like HL-60 myeloid leukemia cells by reducing the gene and protein level of HuR, the MMP-9 mRNA stabilizing nuclear factor." (PMID 37175113, 2023). "Research has shown that IL-18 promoted the invasive ability of HL-60 human myeloid leukaemia cells by up-regulating MMP9 expression." (PMID 36353102, 2022). "Pro apoptotic effects have been described for gelatinase B/MMP-9 in the presence of proneurotrophins, in cerebellar neurons and retinal ganglion apoptosis, in hypertrophic growth plate chondrocytes and in HL60 pro-myelocytic leukaemia cells." (PMID 24473089, 2014). "Conversely, we showed that inhibition of MMP-9 largely restored the levels of NKG2D-, NKp30- and Perforin-positive NK-92 cells, the secretion of TNF-α and IFN-γ and the cytotoxicity on NK cells against myelogenous leukemia K562 cells." (PMID 25274283, 2014).
nonalcoholic fatty liver (5 papers, 2016 to 2025). "MMP9 and TREM1 were identified as hub genes in PCOS patients with non-alcoholic fatty liver (NAFLD)." (PMID 37537636, 2023).
paroxysmal AF (5 papers, 2011 to 2024). "In previous studies, the reported changes in the MMP-9 levels in patients with paroxysmal AF were inconsistent and various diseases may cause inflammation and increase the levels of inflammatory factors." (PMID 27276393, 2016). "From paroxysmal AF through persistent AF to permanent AF, the plasma levels of MMP-9 showed a significant gradual increase." (PMID 28785588, 2017). "In obese patients, MMP-9 can be used to predict the occurrence of paroxysmal AF." (PMID 38643140, 2024). "To summarize, galectin-3, MMP-9, GDF-15, and PIIINP are promising markers in the prediction of paroxysmal AF, while TGF-β1 shows a lower potential." (PMID 28785588, 2017).